CD4 (CD4 molecule)
Diseases named in the same sentence as CD4 in open-access papers (continued):
Sharing a sentence is not in itself a finding about the gene and the disease.
acute myeloid leukemia (46 papers, 2011 to 2025). Acute myeloid leukemia (AML) is a group of neoplasms arising from precursor cells committed to the myeloid cell-line differentiation. "These events have been linked to increased IL17 and reduced IL4 expression in CD4+ T cells in Azacytidine-treated acute myeloid leukemia (AML) and myeloid dysplastic syndrome (MDS) patients." (PMID 33859645, 2021). "We previously showed that adequate CD4 recovery is associated with a lower chance for relapse in acute myeloid leukemia (AML) and with higher survival chances for patients with adenoviral reactivation." (PMID 32974239, 2020). "Enhanced expression of miR-24-3p in exosomes released by acute myeloid leukemia (AML) blasts (R-EXOs) results in increased apoptosis of major CD4+ and CD8+ T lymphocyte subtypes but the promotion of Treg development." (PMID 38339220, 2024). "Using murine models, some authors developed a bone marrow transduction and transplantation approach to develop a model for FGFR1OP2-FGFR1 disease, documenting the appearance of CD4+ T-cell lymphoblastic lymphoma and acute myeloid leukemia." (PMID 36698221, 2023). "For instance, CD4 is expressed in 65.0% and 78.3% of the acute myeloid leukemia and acute monocytic leukemia, respectively, but only in 30–40% of other subtypes." (PMID 37330575, 2023). "Co-culture experiments were conducted using clinical samples from two patients with CD4+ acute myeloid leukemia (PT1 and PT2)." (PMID 31413761, 2019). "CD4+CD25+Foxp3+ regulatory T cells (Tregs) accumulate in bone marrow microenvironment in acute myeloid leukemia (AML)." (PMID 30319662, 2018). "CTLA-4 overexpression has been reported in CD4+CD25+ T cells co-cultured with IDO-expressing acute myeloid leukemia (AML) cells, and this effect is completely abrogated by the IDO-inhibitor 1-methyl tryptophan (1-MT)." (PMID 36713558, 2022). "When CD4+ T cells are cultured with Bregs from acute myeloid leukemia (AML), Tregs are significantly increased." (PMID 36211467, 2022). "A clinical study also showed that IL-35 produced by Treg cells promoted the growth of acute myeloid leukemia (AML) blasts in adult AML patients by limiting the activity of CD4+CD25− T effector cells and increasing cancer cell proliferation." (PMID 33418929, 2021). "Intratumoral accumulation of CD4+CD25+Foxp3+ regulatory T (Treg) cells occurs in acute myeloid leukemia (AML), but little is known about the role of tumor cells themselves in this process." (PMID 32849603, 2020). "Recent studies have shown that acute myeloid leukemia (AML) cells that express IDO can transform CD4+CD25-T cells into CD4+CD25+T cells." (PMID 21917155, 2011). "Research has shown that in patients with acute myeloid leukemia (AML), the expression of GARP on CD4+ T cells is elevated, leading to increased levels of TGF-β1." (PMID 39635528, 2024). "We employed multi-color flow cytometry to evaluate the frequencies of CD103+CD4+ and CD103+CD8+ T cells in the peripheral blood (PB) of patients with acute myeloid leukemia and B-cell acute lymphoblastic leukemia compared to healthy individuals." (PMID 39391310, 2024). "In acute myeloid leukemia, PD1 expression is observed on T-cell subpopulations, including CD4+ effector T cells, CD4+ Treg, and CD8+ T cells, both in untreated patients and in relapses." (PMID 35216084, 2022). "For example, in breast cancer, acute myeloid leukemia (AML) and lung cancer, the highest TNFR2 expression levels were found on Foxp3+CD25+CD4+ Tregs." (PMID 35681583, 2022). "A recent experiment showed that in patients with acute myeloid leukemia, IDO-expressing tumor cells can induce the transformation of CD4+CD25-T cells to CD4+CD25+T cells." (PMID 21917155, 2011). "This study aimed to determine the frequency of regulatory T cells (Tregs) (CD4+/FOXP3+) and indoleamine 2,3-dioxygenase (IDO) expression in patients with acute myeloid leukemia (AML)." (PMID 39695001, 2024).
acute myeloid leukemia (continued). "Multiple studies on Acute Myeloid Leukemia (AML) have observed significant expression of PD-L1 on CD34+ blasts, CD4+/8+ T cells, and Tregs, particularly in bone marrow samples from R/R patients." (PMID 38627681, 2024). "A potential immunotherapy approach for acute myeloid leukemia (AML) may be implemented through the application of HLA ligands, which could allow several established AML-related antigens, including PRTN3, to attract additional CD4+ T-cell epitopes." (PMID 37231509, 2023). "Moreover, Plebanski’s group reported that, in acute myeloid leukemia (AML) patients, combination therapy with lenalidomide and a demethylating agent, azacitidine, downregulated TNFR2 expression on CD4 T cells and reduced the number of TNFR2+ Tregs, resulting in enhanced effector immune function." (PMID 29632537, 2018). "Cell-type specific methylation patterns between acute myeloid leukemia (AML), myelodysplastic syndrome (MDS), and CD4+ CD8+ T cell acute lymphoblastic leukemia (T-ALL) that develop in Mx-1-Cre;Dnmt3afl/fl mice have been previously reported." (PMID 27677595, 2016). "A research study on primary human acute myeloid leukemia showed that HLA-DBP1 specific TCRs genetic transfer into CD4+ and CD8+ T cells could provide an enhanced immune reaction to AML blasts via cytolytic activity and IFN-gamma production in the AML xenograft mouse model." (PMID 35831411, 2022).
bacteremia (46 papers, 2009 to 2025). "Death was significantly associated with NTM bacteremia (p = 0.022) and those patients who died had lower CD4 count at the start of anti-mycobacterial treatment than those who survived (p = 0.034)." (PMID 26985832, 2016). "Features most associated with bacteremia included higher temperature, lower CD4+ T-lymphocyte count, lower hemoglobin, and headache." (PMID 24386229, 2013). "HIV patients with decreased CD4+ T cell counts have increased susceptibility to SA bacteremia." (PMID 33312179, 2020). "Once the first dozen cases of bacteremia were confirmed, we reviewed the clinical records of bacteremic patients and identified lower hemoglobin, higher temperature, lower body mass index (BMI), and lower CD4 count as apparent risk factors." (PMID 24386229, 2013). "In both bivariate and multivariate models of associations between different clinical and laboratory characteristics and confirmed bacteremia, the clinical characteristics most significantly associated with bacteremia included lower CD4 count, higher temperature, lower hemoglobin, and headache." (PMID 24386229, 2013). "Another case involved renal abscess with disseminated metastatic infection, bacteremia, and septic pulmonary emboli, in a patient with a low CD4 count (80 cells/mm3), requiring nephrectomy." (PMID 40747162, 2025). "Hospitalization is strongly recommended for PLWH with CD4 counts <100 cells/μL or uncontrolled HIV viremia, due to the high risk of necrotizing lesions, bacterial sepsis, and systemic complications." (PMID 41472229, 2025). "IFN-γ secreting CD4+ T cells were identified for only one patient with a high bacteremia score (group 2)." (PMID 38969796, 2024). "The concentrations of cytokines and the proportions of IFN-γ secreting CD4+ T cells were measured serially during the bacteremia period." (PMID 38969796, 2024). "Amongst the lymphocyte subsets the relative proportion of B cell (B naïve) and T cell subtypes (CD8, and CD4 naïve, and CD4 memory) were found to be lower in Bacteremia compared with Healthy Controls." (PMID 38817614, 2024). "Translating these findings, we found that CD4+ T cells are an important source of IFN-γ production during bacteremia and they play an important role in bacterial clearance and contribute to disease severity in SAB PB." (PMID 38969796, 2024). "The proportion of IFN-γ-secreting CD4+ T cells were the highest just before the positive-to-negative conversion of blood cultures in patients with a low Pitt bacteremia score and those who survived for 12 weeks." (PMID 38969796, 2024). "The most significant finding is that IFN-γ producing CD4+ T cells play an important role in bacterial clearance during bacteremia and affect disease severity." (PMID 38969796, 2024). "The highest CFR (26.7%, 16/60) was reported during hospitalisation for PLHIV with CD4 counts < 350 cells/mm3 and included death due to suspected bacterial sepsis and disseminated TB." (PMID 36814335, 2023). "Higher immune cell counts for both bacterial sepsis and septic shock patients were noted, especially in B cells, classical monocytes, CD4 and CD8 naïve T cells, and natural killers." (PMID 36979757, 2023). "In this NHP study, we demonstrated that the depletion of CD4+ T cells by anti-CD4 mAb treatment led to very early Mtb dissemination (bacteremia) after pulmonary infection." (PMID 33732233, 2021). "Patients with paradoxical-IRS had marginally lower CD4 count and higher frequency of bacteremia than those with unmasking-IRS (p = 0.051, and 0.059)." (PMID 26985832, 2016). "CD4+CD25+ T cell levels were higher in the CMt recovered cats when compared with the acutely infected cats following the onset of bacteremia." (PMID 23216686, 2012). "The cats that had recovered from previous bacteremia showed higher CD4+ T cell levels when compared with acutely infected cats at several time points after the CMt inoculation." (PMID 23216686, 2012).
bacteremia (continued). "In conclusion, SA bacteremic patients had increased frequency of CD4+CD161+ T cells compared to healthy controls suggesting that type II NKT cells could be relevant in the human setting for combatting SA bacteremia." (PMID 33312179, 2020). "Acquisition of STm-specific CD4+ T cells in early childhood parallels the age-related increase in incidence of STm bacteremia, suggesting that the early acquisition of T-cell immunity to NTS alone is insufficient to protect against iNTS disease and that additional immune modalities are required." (PMID 24443544, 2014). "The increased number of FadA- and Td92-specific CD4+ T cells in patients, particularly after CP treatment, may reflect frequent bacteremia and the repeated activation of specific T cells." (PMID 23335969, 2013). "The observed associations between bacteremia and higher temperature, lower hemoglobin, and lower CD4 count in our study subjects may be of use in the development of clinical prediction rules for bacteremia diagnosis." (PMID 24386229, 2013). "This phenotype was in contrast to experimental bacteremia studies where the SEB and SEC staphylococcal superantigens promoted liver abscess formation through a CD4-dependent and excessive IFNγ response." (PMID 39840991, 2025). "Similarly, the increased prevalence of adipokines, such as Leptin, in patients with COPD obesity has been shown to promote the shift of CD4+ T cells to Th1 cells, which may improve macrophage phagocytosis, bacterial clearance and reduce the incidence of bacteremia." (PMID 39450126, 2024). "Among the seven T cell subsets, five cell subsets were differentially expressed in viral sepsis compared to bacterial sepsis, including up-regulated CD8+ T cell, naïve CD4+ T cell, resting memory CD4+ T cell, Tregs, and down-regulated gamma-delta T cell." (PMID 37077915, 2023). "Preclinical studies have shown that bacterial sepsis leads to increased expression of CTLA-4 on CD4+ and CD8+ T cells, and anti-CTLA-4 treatment exhibits dose-dependent reductions in CD4+ and CD8+ T lymphocyte apoptosis and improved survival." (PMID 36518755, 2022). "Reduction in the counts of all lymphocyte subsets (total T cells, CD4+ T cells, CD8+ T cells, B cells, and NK cells) were common for both bacterial sepsis and SARS-CoV-2 sepsis groups." (PMID 33329592, 2020). "We have previously reported differential effects of bacterial sepsis on PD-1 and PD-L1 in CD8 versus CD4 T cells." (PMID 26786705, 2016). "At times of peak bacteremia, a decrease in eosinophils and lymphocytes, as well as subsets thereof (B lymphocytes and CD5+, CD4+ and CD8+ T lymphocytes), and an increase in monocytes were particularly significant in the passively immunized cats." (PMID 27496124, 2016). "The proportion of IFN-γ-secreting CD4+ T cells was highest just before the blood cultures turned negative for patients with low Pitt bacteremia scores and those who survived for 12 weeks." (PMID 38969796, 2024). "The proportion of IFN-γ secreting CD4+ T cells tended to be correlated with the IFN-γ concentration and was significantly high 1–3 days before the last positive culture day for 15 patients with low bacteremia scores (group 1)." (PMID 38969796, 2024). "LAM test characteristics were not different in patients with bacteremia but showed higher sensitivity and lower specificity with decreasing CD4 cell count." (PMID 22412939, 2012). "Patients with Mycobacterium tuberculosis (MTB) bacteremia (25/249) had higher in-hospital mortality (OR 1.97, 95% CI = 1.19–327) and lower median CD4 counts (p = 0.001) than patients without MTB bacteremia." (PMID 19907656, 2009). "Finally, we determined that the expression of IL-1R on γδ T cell, but not CD4+ or CD8+ T cells was responsible for survival against the S. aureus bacteremia." (PMID 37483624, 2023). "Also in this study it was noted HIV patients with bacteremia had significantly lower CD4+ count than HIV patients without bacteraemia, a finding that is similar to other studies." (PMID 23075077, 2012).
bacteremia (continued). "Advanced HIV (CD4 cell count <100cells/mm3), male gender and positive urine TB LAM test predicted presence of MTB bacteremia among smear-negative clinically suspected TB patients." (PMID 25888317, 2015). "Furthermore, differences were found in the total T cell, CD4+ T cell, and CD8+ T cell counts between bacterial sepsis survivors and nonsurvivors." (PMID 33329592, 2020). "Compared to patients without MTB bacteremia, however, patients with MTB bacteremia had a significantly lower median CD4 count (17 vs 64 lymphocytes/mm3, p<0.001) and fewer were taking highly active anti-retroviral therapy (HAART) at the time of hospitalization (92% vs 72%, p<0.001)." (PMID 23940557, 2013). "Although populations of non-CD4 lymphocytes, such as CD8+ memory T cells, natural killer (NK) cells and double-negative (DN) T cells significantly expanded after IL-2/anti-IL-2 complex treatment, progressive development of bacteremia and pathologic lung alterations could not be prevented." (PMID 27391012, 2016).
hypogammaglobulinemia (46 papers, 2011 to 2025). "In conclusion, impaired TCR-mediated activation of CXCR5-negative CD4+ memory T cells following stimulation with vaccine antigen or superantigen identifies patients with primary antibody deficiency and impaired IgG responses after BNT162b2 vaccination." (PMID 35237272, 2022). "We report herein a novel presentation of leaky RAG1/RAG2 deficiency which is associated with selective IgG antibody deficiency and massively decreased numbers of naïve CD4+ T-cells." (PMID 26186701, 2015). "Herein we explore the functional alteration of the hemizygous variant c.172C>A, p.(Pro58Thr) in IL2RG found in an adult patient who has been followed-up at our Clinical Immunology department for more than three decades for a CVID-like antibody deficiency with low T CD4+ counts." (PMID 40170851, 2025). "The patients also exhibited CD4+ and TemCD4+ deficiency which, together with hypogammaglobulinemia, might explain their susceptibility to infections." (PMID 34867966, 2021). "Examination of the functional activity of CD4+ T cells in response to viral antigens in individuals with agammaglobulinemia showed results comparable to those in healthy ones." (PMID 39203969, 2024). "Reduced naïve CD4T cells, reversed CD4/CD8 ratio, diminished vaccine responses, and hypogammaglobulinemia characterize DEF6 mutations." (PMID 38535602, 2024). "Our data also shows that most patients with hypogammaglobulinemia produce CD4+ and CD8+ cellular responses against all tested viral variant spike peptides already after the first vaccine dose." (PMID 37234151, 2023). "Comparison of T cell counts in patients with PID and secondary hypogammaglobulinemia revealed a significantly higher percentage of memory CD4+ T cells and CD4+ T follicular cells in cases of primary hypogammaglobulinemia than in those with secondary." (PMID 32272789, 2020). "Subsequent immunological assessment revealed agammaglobulinemia and B-cell deficiency (0.47%) associated with decreased CD45 RA+ naive CD4+ T-cells (4.5% of CD4+ T-cells)." (PMID 32169066, 2020). "This difference in proportion of memory CD4+ T cells and CD4+ T follicular cells among CD4+ T cells corresponded to increased absolute cell counts in the PID group as compared to secondary hypogammaglobulinemia." (PMID 32272789, 2020). "Our data revealed that the patient’s hypogammaglobulinemia is associated with CTLA-4 haploinsufficiency, increased JAK3 activity, and increased percentages of circulating CD4+ and CD8+ effector memory T cells." (PMID 29375547, 2017). "Reduced CD4+ T and B lymphocyte counts, hypogammaglobulinemia were observed." (PMID 39823049, 2024). "Due to hypogammaglobulinemia, immunoglobulin deficiency, and alterations in immunophenotyping with low levels of CD3/CD4 and CD19 cells, he was given intravenous human immunoglobulin (IVIG) replacement at a dose of 400 mg/kg at 28-day intervals, and he showed significant improvement." (PMID 37764964, 2023). "In summary, peripheral lymphocyte subset counts and especially measurement of CD4+ T follicular helper cells and class-switched memory B cell counts could aid differentiation of primary from secondary hypogammaglobulinemia." (PMID 32272789, 2020). "In order to further investigate the relationship between B cells and the IL-17-producing CD4 subset, we evaluated this population in individuals with Congenital Agammaglobulinemia, who lack mature B cells due to genetic defects impairing early B-cell development." (PMID 21826211, 2011). "Although our patient presents CD4+ T cell lymphopenia and antibody deficiency, we assessed normal CD4+ and CD8+ cell proliferation with CD3/CD28 and in B cells with both T cell dependent stimuli (CD40L and IL-21) and the combination of T cell dependent and independent stimuli." (PMID 40170851, 2025).
hypogammaglobulinemia (continued). "The proportions of memory CD4+ T cells and CD4+ T follicular cells, as well as those of naïve B cells, class-switched memory B cells and CD21low B cells, displayed adequate but still low sensitivity and specificity for the discrimination of primary from secondary hypogammaglobulinemia." (PMID 32272789, 2020). "In a previous study, secondary antibody deficiency as a consequence of glucocorticoid therapy with or without methotrexate has been associated with reduced naïve and transitional B cells as well as with reduced CD4 memory T cells." (PMID 32272789, 2020). "Next, SARS-CoV-2 spike (S)-specific CD4+ and CD8+ T cell responses were assessed from hypogammaglobulinemia patients (n=31) and immunocompetent HCWs (n=10) with activation induced marker (AIM) assay." (PMID 37234151, 2023). "CD4+ and CD8+ cellular responses were quite similar between all subgroups of hypogammaglobulinemia, and CVID patients have almost equally strong cell-mediated immune responses compared to immunocompetent HCWs." (PMID 37234151, 2023). "In patients with agammaglobulinemia, there was no S-specific cytokine expression by CD4 T lymphocytes, but consistent IFN-γ and TNF-α expression by CD8+ T cells." (PMID 38132279, 2023). "Patients with STAT3 GOF mutations predominantly presented with lymphoproliferation, characterized by elevated frequencies of double-negative (CD4− CD8−) T cells, autoimmune hematopenia, and hypogammaglobulinemia." (PMID 40703313, 2025). "Four percent (3/68) exhibited only immunological abnormalities in the absence of a clinical related phenotype: one patient had hypogammaglobulinemia and decreased CD19 + and CD4 + cells, second had decreased TH17 and third hypogammaglobulinemia and decreased CD19 + cells." (PMID 38231401, 2024).